IGHV1-45 (immunoglobulin heavy variable 1-45)
Description:
V region of the variable domain of immunoglobulin heavy chains that participates in the antigen recognition. Immunoglobulins, also known as antibodies, are membrane-bound or secreted glycoproteins produced by B lymphocytes. In the recognition phase of humoral immunity, the membrane-bound immunoglobulins serve as receptors which, upon binding of a specific antigen, trigger the clonal expansion and differentiation of B lymphocytes into immunoglobulins-secreting plasma cells. Secreted immunoglobulins mediate the effector phase of humoral immunity, which results in the elimination of bound antigens. The antigen binding site is formed by the variable domain of one heavy chain, together with that of its associated light chain. Thus, each immunoglobulin has two antigen binding sites with remarkable affinity for a particular antigen. The variable domains are assembled by a process called V-(D)-J rearrangement and can then be subjected to somatic hypermutations which, after exposure to antigen and selection, allow affinity maturation for a particular antigen.
Synonyms: IGHV145; VH
Gene: Immunoglobulin variable (V) gene on chromosome 14 (106,506,996 to 106,507,491, reverse strand). Ensembl gene ENSG00000211961.
Subcellular location: Secreted; Cell membrane
Gene Ontology:
Molecular function: antigen binding
Biological process: immunoglobulin mediated immune response
Cellular component: extracellular region; plasma membrane
Homologues: Orthologues: chimpanzee IGHV1-45 (86% identical), macaque IGHV1-45 (74% identical), mouse Ighv1-53 (63% identical), mouse Ighv1-64 (62% identical), mouse Ighv1-74 (62% identical), mouse Ighv1-50 (62% identical), mouse Ighv1-52 (62% identical), mouse Ighv1-55 (62% identical), mouse Ighv1-61 (62% identical), mouse Ighv1-69 (61% identical), mouse Ighv1-11 (60% identical), mouse Ighv1-4 (60% identical), and 49 more. Paralogues in human: IGHV1-3 (83% identical), IGHV1-2 (81% identical), IGHV1OR15-1 (80% identical), IGHV1-18 (79% identical), IGHV1-58 (78% identical), IGHV1-69 (77% identical), IGHV1-69D (77% identical), IGHV1-46 (76% identical), IGHV1OR21-1 (74% identical), IGHV1-24 (73% identical), IGHV1OR15-9 (73% identical), IGHV1-69-2 (70% identical), and 65 more.